GPX2 (glutathione peroxidase 2)
Diseases named in the same sentence as GPX2 in open-access papers (continued):
Sharing a sentence is not in itself a finding about the gene and the disease.
cancer (continued). "Moreover, GPx2 knockout in mice resulted in intestinal tumorigenesis and sensitized their skin to cancer by irradiation." (PMID 39125992, 2024). "While low levels of GPx3 are associated with a poor prognosis in several cancers, its upregulation in PDAC is linked to reduced ROS levels and increased chemoresistance together with superoxide dismutase (SOD1) and peroxidases (GPx2, thyroperoxidase, and myeloperoxidase)." (PMID 39594547, 2024). "It has been suggested that GPX2 expression is tumor-stage-dependent, and upregulation of GPx2 in early-stage carcinomas might protect tumor cells from the effects of ROS on oncogenic signaling, leading to neoplastic progression." (PMID 39125992, 2024). "Glutathione peroxidase 2 (Gpx-2) is a selenoenzyme with antioxidant capabilities that may play a role in cancer development." (PMID 37834097, 2023). "PL restored ROS level (mainly via reversing Duox2/Gpx2), activated oxidative stress/inflammation/immune responses signature genes, reduced cancer cell proliferation/invasion, increased apoptosis and CD3+/CD4+/CD8+ T-lymphocytes in G422TN-tumor on the basis of RT/TMZ regimen." (PMID 37161450, 2023). "The results of these in vitro experiments clearly showed that Gpx-2 may be involved in cancer progression, probably by activating EMT and signalling pathways associated with this process." (PMID 37834097, 2023). "Therefore, GPx2 seems to have differential roles depending on the transformation stage of cancer cells." (PMID 36672389, 2023). "GPx2 is found in epithelial tissues and digestive tract epithelium, and it may be a prognostic factor in cancers." (PMID 37138031, 2023). "The role of GPx-2 in cancer has been described in the last few years." (PMID 37761814, 2023). "This physiological function might become deleterious with cancer cells, and GPx2 has indeed been shown to be upregulated in several epithelial cancers, which may be all linked to Wnt activation." (PMID 37373256, 2023). "Moreover, GPx2 knockout in mice resulted in intestinal tumorigenesis and sensitized skin to cancer by irradiation." (PMID 35193955, 2022). "GPx3 is considered a tumor suppressor, GPx2 seems to act at the very early stages of cancer, while selenoprotein H is a key regulator for the cell cycle, indicating the role of selenoproteins in cancer could be both preventive and therapeutic." (PMID 35682497, 2022). "We suspect GPx2 up-regulation in early-stage carcinomas might protect tumor cells from the effects of ROS on oncogenic signaling, leading to neoplastic progression." (PMID 35193955, 2022). "Previous studies have suggested that high GPX2 gene expression is associated with a poor cancer prognosis, which appears to be supported by the present finding of a significant negative correlation between the GPX2 and GPX3 genes." (PMID 33706760, 2021). "This implies the variety of GPX2 features in different types of cancers." (PMID 33552592, 2021). "The project then detected the expression profiles of GPX2 in various cancer cell lines in CCLE." (PMID 33552592, 2021). "In recent years, the role of GPX2 in cancers has been elucidated." (PMID 33552592, 2021). "However, several reports including our previous study described that a high GPX2 expression supported the growth of cancer cells by facilitating their proliferation via inhibition of oxidative damage-induced apoptosis." (PMID 29662611, 2018). "On the other hand, GPX2 has also been shown to contribute to the progression of malignant tumor." (PMID 29662611, 2018). "As expected, the expression of GPX2 protein is up-regulated within various cancer tissues." (PMID 27388201, 2016).
cancer (continued). "So far, it has been shown that changes in the activity of the GPX1, GPX2, and GPX3 isoforms may be associated with the development of cancer." (PMID 26682223, 2015). "This indicates that GPx2-KO mice are more resistant to AOM-induced cancer." (PMID 23977205, 2013). "Indeed, GPx2 expression is higher in proliferating cancer stem cells compared to their differentiated progeny." (PMID 22654914, 2012). "However, if a cell has been transformed into a malignant cell and the carcinogenic process has started, the cancer cells will equally profit from the protective roles of TrxR1, GPx2, and other Nrf2 programs and, accordingly, will grow unhampered." (PMID 22654914, 2012). "In addition, another study demonstrated that NRF2 enhances the expression of the antioxidant enzyme GPX2, which plays a pivotal role in maintaining cancer stem cell populations through the upregulation of NOTCH3, a key driver of tumor progression.NRF2 also has other pro-tumorigenic functions." (PMID 41187427, 2025). "Consistent with this, Gpx2 abrogation led to the repression of transcriptional programs implicated in stem cell pluripotency, including the WNT, Hippo–YAP and TGFβ pathways, as well as epithelial–mesenchymal transition and other processes involved in cancer cell fitness." (PMID 38658753, 2024). "Thus, the under-expression of GPX2 following exposure to juçara fruit compounds may be useful in cancer therapy, based on the reduced antioxidant defense potential shown in HT-29 and Caco-2 cells." (PMID 37075346, 2023). "However, several studies also indicated that some selenoproteins, namely important cellular redox regulators TXNRD1, SELENOF, and GPx2, may both prevent and promote cancer." (PMID 34829750, 2021). "The cancer preventive effects, as well as other health benefits, of this micronutrient have primarily been linked to the oxidoreductase function of these selenoproteins, particularly thioredoxin reductase 1 (TR1), 15 kDa selenoprotein (Sep15) and glutathione peroxidase 2 (GPx2)." (PMID 29304040, 2018). "Also Nrf2 targets may have dual roles in cancer which will here be discussed for the selenoproteins thioredoxin reductase-1 (TrxR1) and glutathione peroxidase-2 (GPx2)." (PMID 22654914, 2012). "Mechanistically, GPX2 triggers Hedgehog signaling activation through releasing GLI transcriptional regulator, promoting cancer stem cell (CSC) characteristics and TKI resistance." (PMID 40533443, 2025). "Elevated RNA expression of cytochrome monooxygenases (CYP4F11 and CYP4F3) and glutathione peroxidase 2 (GPX2), among others, was found in smoking-related malignancies that had minimal baseline leukocyte infiltration." (PMID 40723371, 2025). "Se nanoparticles also decreased cancer cell viability and proliferation while increasing the mRNA expression of TXN, GPX1, GPX2, GPX3, and GPX4 in many of the cancer cell lines." (PMID 39408290, 2024). "We assessed 19,221 genes and observed a positive correlation between FIN sensitivity and the expression of several well-known NRF2 targets, including NQO1, SLC7A11, GPX2, GCLC, and FTH1, across various cancer cell lines at both the mRNA and protein levels." (PMID 37633973, 2023). "In most cancers, GPX2, HNF4A, and STMN1 were hypomethylated, while the majority of cancer genes exhibited hypermethylation." (PMID 37304867, 2023). "GPX2 knockdown is followed by NRF2-induced upregulation of GPX2 and cytochrome c oxidase 2 (COX2), revealing the suppression of inflammation-mediated cancer." (PMID 36324584, 2022). "NTS is highly positively correlated with the expression of the cancer-promoting factors CPS1, FGG, and GPX2 in a subgroup of NSCLC." (PMID 33493519, 2021). "To date, studies of selenoproteins raised on the association between Se supplements and cancer prevention, as well as GPX1, GPX2, and GPX3, have been reported with major physiological roles of cancer prevention or development." (PMID 32316597, 2020).
cancer (continued). "Through our analysis, we confirmed higher levels of GPX2 and TXNRD1, and lower levels of GPX1, SELENOF, and SELENOP in the cancer cell lines compared to normal epithelial cells, which has already been observed and reported in the literature." (PMID 32933107, 2020). "As to using cell lines to model cancer etiology, the top-down model would suggest a likelihood that the source cells lacked GPX2 expression and gained it as a function of progress along the malignancy continuum." (PMID 39329876, 2024). "Enzymes mitigating oxidative stress, like superoxide dismutase (SOD) and glutathione peroxidase 2 (GPX2), are essential in neutralizing reactive oxygen species produced during radiation therapy, further contributing to the resilience of cancer cells against radiotherapy." (PMID 38132173, 2023). "Notably, high expression of GPX2 is useful in controlling inflammation by inhibiting COX2; however, in CRC, it increases the rate of cell proliferation and decreases apoptosis in cancer cells." (PMID 37075346, 2023). "For example, GPX2 is mainly expressed in the gastrointestinal tract, and the three cancers with the highest expression levels were COAD, READ, and STAD, while the other cancers showed a trend of low expression especially in the GBM, KIRC, KIRP, and THCA." (PMID 33706760, 2021). "In addition, the patients with a high level of GPX2 expression in their TUR specimen showed significantly better progression-free survival (PFS), cancer-specific survival (CSS), and overall survival (OS) than those with low level of GPX2 expression." (PMID 29662611, 2018). "For example, GPx1 and GPx2 help control the production of pro-inflammatory prostaglandins by regulating COX-2, suggesting that these enzymes may have protective roles in inflammation-related diseases like colitis and cancer." (PMID 39942544, 2025). "Additionally, GPX1, GPX2, and GPX4 expression is upregulated in cancer cells resistant to many chemotherapeutics, and many treatment-resistant cells have been found to accumulate lipid peroxides, showing an increased dependence on the antioxidant activity of GPX4." (PMID 37244126, 2023). "Hence, the classification effectiveness of ten biomarkers which was assessed overall was based on GPX2 and GPX3 as factors from the enriched pathways and CAV1, ENO1, NQO1, and P4HB as factors from functional classes to determine whether a patient had cancer." (PMID 37955007, 2023). "In cancer, GPX1 and GPX3 are tumor suppressors, while GPX2 may have dual roles in tumorigenesis." (PMID 36443446, 2022). "Additionally, the silencing of GPx2 has been shown to reduce the expression of metalloproteinases (MMPs) MMP2 and MMP9 by downregulation of the Wnt pathway and inhibition of inflammation-mediated carcinogenesis, which are critical for cancer cell proliferation, migration, and invasion." (PMID 39594547, 2024). "The undesirable effect of GPx2 in cancer development may not be trivial, however." (PMID 37373256, 2023). "Finally, by testing the relationship between the expression levels of these two families of selenoprotein genes in NCI-60 cell lines and drug sensitivity, we found that the TXNRD1, GPX1, GPX2, and GPX3 genes may play a role in the drug sensitivity or drug resistance of cancer cells." (PMID 33706760, 2021). "This might be due to the absence of another GPX isoenzyme in monocytes, GPX2, which has been previously shown to have overlapping functions with GPX1 in limiting the redox-dependent activation of the NF-κB pathway and LM biosynthesis in human epithelial-derived cancer cells." (PMID 34681720, 2021).
tumor (77 papers, 2012 to 2026). "Elevated GPX2 expression correlates with poor prognosis and is associated with larger tumor size, LN metastasis, and higher TNM stage." (PMID 40740483, 2025). "The expression of Glutathione Peroxidase 2 (GPX2) is associated with tumor metastasis of rat HCC both in vitro and in vivo." (PMID 40051627, 2025). "On the other hand, Se-deficient GPX2-knockout mice exhibit smaller tumor size compared to the wild-type genotype in chemically induced models of tumors." (PMID 41300456, 2025). "In contrast, it has been found that the loss of GPx2 in breast, bladder, and esophageal carcinomas led to tumor progression and worse prognosis." (PMID 39125992, 2024). "Examination of similarly-sized control PyMT and PyMT/GPx2 KD tumours confirmed that GPx2 KD actively promotes metastasis, thus ruling out hypoxia caused by tumour bulkiness as the impetus for advancing malignancy." (PMID 38238426, 2024). "GPX2-deficient mice were protected from azoxymethane-induced colorectal tumorigenesis, which is demonstrated by the tumor-initiating activity of the antioxidant GPX2." (PMID 37107276, 2023). "Our study confirmed that GPx2 was overexpressed in GC tissues and was closely associated with tumor metastasis and survival outcomes in GC patients." (PMID 37138031, 2023). "In the present study, we determined that GPx2 is highly expressed in GC tissues and is closely associated with tumor metastasis and survival outcomes in GC patients." (PMID 37138031, 2023). "Ingenuity Pathway Analysis revealed a link between GPx2 loss, tumor angiogenesis, metabolic modulation, and HIF1α signaling." (PMID 35193955, 2022). "Overlay of the differentially expressed genes by GPx2 KD onto the genes underlying OXPHOS in the Ingenuity Knowledge Base led IPA to predict that oxygen consumption in the GPx2 KD tumor was in fact inhibited." (PMID 35193955, 2022). "This suggested that GPx2 loss impairs the vasculature by causing insufficient oxygen delivery to the tumor, which was consistent with the dense and tortuous vasculature observed in GPx2 KD tumors." (PMID 35193955, 2022). "In sum, GPx2 loss exert broad effects on the tumor phenotype that are consistent with ROS oncogenic signaling." (PMID 35193955, 2022). "Our data underscore the notion that GPx2 loss drives tumor heterogeneity, resulting in a metabolically hybrid tumor cell population, which in turn activates both AMPK and HIF1α (GLUT1) signaling, likely due to ROS signaling." (PMID 35193955, 2022). "Our study also found a positive correlation between the GPX2 gene and RNAss, suggesting that the expression of this gene in tumor cells is associated with a poor prognosis." (PMID 33706760, 2021). "Using colonosphere cultures of tumor cells recently revealed that loss of GPx2 is associated with enhanced stem cell formation, highlighting differences between functions of GPx2 in tumor models and non-tumor systems." (PMID 29416634, 2018). "Larger tumors in the GPx2-KO were linked to a tumor-promoting environment characterized as low-grade inflammation." (PMID 23977205, 2013). "Tumors produced by AOM/DSS treatment were smaller in GPx2-KO than in WT mice as were tumor xenografts derived from GPx2-deficient HT-29 cells compared to control cells." (PMID 23977205, 2013). "Tumor development was monitored in GPx2-KO and WT mice fed a moderate selenium-deficient (−Se), -adequate (+Se) or -supranutritional (++Se) diet." (PMID 23977205, 2013). "Moreover, GPX2 overexpression has been linked to the formation of differentiated tumor mass and early recurrence of CRC, potentially by counteracting ROS overproduction." (PMID 41300456, 2025). "However, after blue-light-mediated oncogenic recombination, GPX2-deficient mini-colons developed tumours with reduced kinetics and multiplicity, recapitulating the results obtained with tiopronin." (PMID 38658753, 2024).
tumor (continued). "This phenomenon may be a common mechanism with which Gpx-2 promotes malignancy in adenocarcinoma-derived tumours that are susceptible to oxidative stress." (PMID 37834097, 2023). "Moreover, analysis of each of the tumor cell clusters showed that GPx2 KD caused cluster 5 to be highly enriched in OXPHOS genes relative to all other clusters, as judged by the -log (P value), relative to moderate enrichment in glycolysis." (PMID 35193955, 2022). "However, GPx2 loss drives tumor heterogeneity, thereby selecting for a tumor subpopulation endowed with phenotypic and metabolic plasticity that likely drives malignant progression." (PMID 35193955, 2022). "In light of the striking effects of GPx2 on the malignant phenotype, we sought to examine the effect of GPx2 loss on tumor heterogeneity at the single-cell level to identify potential cell populations (i.e., clusters) that might drive BC progression." (PMID 35193955, 2022). "Single-cell RNA analysis and bioenergetic profiling revealed that GPx2 loss stimulated the Warburg effect in most tumor cell subpopulations, except for one cluster, which was capable of oxidative phosphorylation and glycolysis, as confirmed by coexpression of phosphorylated-AMPK and GLUT1." (PMID 35193955, 2022). "In addition to normal tissues, it has been reported that GPx2 is upregulated in a variety of tumor cells and is associated with tumor cell proliferation and poor prognosis of patients." (PMID 32571353, 2020). "However, miR-17-3p can inhibit GPX2, altering mitochondrial respiration and consequently rendering tumor cells susceptible to anticancer therapy." (PMID 33228209, 2020). "Our findings indicate that GPX2 is a promising target for anti-tumor therapy and overcoming cisplatin resistance in DGC, presenting a novel strategy for targeting lipid metabolism in GC therapy." (PMID 41145471, 2025). "To assess the broader implications of GPX2 on tumor growth and cisplatin efficacy, we employed a xenograft model using BGC823 cells." (PMID 41145471, 2025). "GPX2 can mediate ROS clearance for metabolic reprogramming and alter signaling pathways to affect tumor development." (PMID 40533443, 2025). "Our in vivo studies revealed that GPX2 overexpression significantly accelerated tumor growth compared to controls." (PMID 41145471, 2025). "A significant upregulation of polymerase (RNA) III (DNA directed) polypeptide G (POLR3G)Glutathione peroxidase 2 was identified in advanced bladder cancer tissues, correlating with aggressive tumor behavior and reduced survival." (PMID 40740483, 2025). "While cisplatin treatment generally suppressed tumor growth, this effect was substantially mitigated in tumors with GPX2 overexpression." (PMID 41145471, 2025). "As an indispensable antioxidant enzyme of GSH metabolism, GPX2 maintains low intracellular ROS level and maintain the clonogenic and metastatic tumor cell population." (PMID 40533443, 2025). "Tumor growth measurement demonstrated that GPX2 knockdown shrank the tumor size, while together with gefitinib made the tumor size diminish much more." (PMID 40533443, 2025). "Remarkably, compared to control tumours which were KRT8 and pAMPK positive, GPx2 KD tumours contained KRT8/KRT14 positive areas that expressed pAMPK (in the cytosol) and GLUT1 (at the membrane) in same cells." (PMID 38238426, 2024). "To study the relationship between lung mets and primary GPx2 KD tumour, we used Seurat to integrate the transcriptomics of both sites, as shown in UMAP." (PMID 38238426, 2024). "By inputting the differentially expressed genes (DEGs) between lung mets and GPx2 KD primary tumour into the Dorothea database, we uncovered a dramatic enrichment of Trp63 target genes in lung mets." (PMID 38238426, 2024). "By contrast, GPx2 OE tumours were reduced in VIM/GLUT1 but increased in E-CAD/pAMPK expression as compared to control tumours." (PMID 38238426, 2024).